CSF1R (colony stimulating factor 1 receptor)
Diseases named in the same sentence as CSF1R in open-access papers (continued):
Sharing a sentence is not in itself a finding about the gene and the disease.
breast cancer (continued). "In line with the variable results of CSF1/CSF1R blockade, CSF1 gene signatures themselves were found to be either associated with poor survival or with improved survival, depending on the specific subtype of breast cancer." (PMID 26635798, 2015). "Eventually, CSF-1R expression could be a promising candidate as demonstrated here in the primary breast cancer data sets of 2082 patients." (PMID 26098772, 2015). "Finally, recent data revealed a switch between invasion and proliferation in claudin-low breast carcinoma cells mediated via an autocrine activation of CSF-1R signalling." (PMID 26098772, 2015). "However these results show that the proliferation potential of both canine mammary carcinoma cell lines tested are dependent on CSF-1R signalling." (PMID 26174804, 2015). "Our results confirmed that the decreased CSF-1R expression is accompanied by the lower ability of cancer cells to invade matrix, whereas the presence of CSF-1 in the culture medium increased canine mammary cancer cells invasion in Matrigel matrix." (PMID 23561040, 2013). "In conclusion, the evidence of the expression and functional role of the CSF-1R in canine mammary cancer cells indicate that CSF-1R targeting may be a good therapeutic approach." (PMID 23561040, 2013). "Our previous study has showed the expression of CSF-1R in all examined canine mammary tumors." (PMID 23561040, 2013). "Thus, the aim of our study was to evaluate the role of CSF-1R in biology of canine mammary cancer cells." (PMID 23561040, 2013). "Similarly, this dose was used by other authors for assessment of the role of CSF-1R in biology of breast cancer cell lines." (PMID 23561040, 2013). "Our results showed that all the examined canine mammary cancer cell lines expressed CSF-1R." (PMID 23561040, 2013). "In human breast cancer, the levels of CSF1R correlate with local relapse after radiation therapy, but do not correlate with metastasis; these data were the first to suggest that high levels of CSF1R might promote radio-resistance." (PMID 24019961, 2013). "The evidence of the expression and functional role of the CSF-1R in canine mammary cancer cells indicate that CSF-1R targeting may be a good therapeutic approach." (PMID 23561040, 2013). "Indeed, interfering with CSF-1/CSF-1R signaling, either by targeting the receptor or by blocking the ligand binding, impacts on breast cancer cell proliferation." (PMID 22096574, 2011). "To test whether an autocrine CSF-1/CSF-1R loop exists in breast cancer cells we used a CSF-1-blocking antiserum." (PMID 22096574, 2011). "Although the expression of CSF-1/CSF-1R has been previously documented in breast cancer and shown to correlate with poor prognosis, few studies have been performed to understand the role of CSF-1R-dependent signaling in the proliferation of breast cancer cells or other solid tumors." (PMID 22096574, 2011). "To determine whether CSF-1R transduces proliferative signals in breast cancer cells we chose two cell lines from different subtypes." (PMID 22096574, 2011). "Moreover, gene expression profiling datasets show that CSF1 and CSF1R expression is a general feature of breast cancer cells." (PMID 22096574, 2011). "However, the expression of CSF-1R and/or CSF-1 has been documented in several human cancers, including carcinomas of breast, female reproductive tract, prostate and kidney." (PMID 22096574, 2011). "Experimental studies also demonstrated that BLZ945, a highly selective small molecule CSF-1R inhibitor, not only inhibits monocyte recruitment into murine breast cancer by 6-fold but may also increase the infiltration of CTLs in cervical and breast carcinomas, relieving immunosuppression." (PMID 40385641, 2025).
breast cancer (continued). "Given the ubiquitous expression of C/EBPβ in various subpopulations of CSF1R-expressing myeloid cells in both the normal mammary gland and a mouse model of breast cancer progression, we hypothesized that macrophage-derived C/EBPβ may be fundamental to macrophage function in the mammary gland." (PMID 39025525, 2024). "Also, CSF-1/CSF-1R inhibitors, including kinase inhibitors and antibodies, can attenuate angiogenesis, metastasis, and proliferation of tumor cells and reprogram cancer cell growth in breast cancer models." (PMID 39003350, 2024). "Thus, the co-expression of CSF-1 and the CSF-1R in cancer cells suggests both autocrine and paracrine mechanisms driving tumor invasion and metastasis as the CSF-1R is highly expressed by TAMs, emphasizing the prognostic value of TAMs, and in turn of the CSF-1R, in breast cancer." (PMID 39457693, 2024). "Several reports have shown that high CSF1R expression decreases the overall survival of follicular lymphoma, correlates with increased invasiveness and adverse prognostic factors such as high histological grade of breast cancer, and shows an advanced clinical stage at detection of breast cancer." (PMID 35887121, 2022). "Our study concluded that the racemic trans-(±)-kusunokinin may have inhibited breast cancer cells primarily through the binding and suppression of CSF1R by trans-(−)-kusunokinin, in addition to the binding of trans-(−) or trans-(+) isomers to other target proteins." (PMID 35807438, 2022). "(−)KU mainly binds to colony-stimulating factor 1 receptor (CSF1R) to suppress breast cancer proliferation, while some trans-(−)-kusunokinin and trans-(+)-isoforms could inhibit intracellular proteins, such as heat-shock protein 90 alpha (Hsp90-α) and aldo-keto reductase family 1 member B1 (AKR1B1)." (PMID 36552555, 2022). "The previous study hypothesized that the trans-(−)-isoform was the preferred active form in the trans racemic mixture, binding CSF1R at the juxtamembrane region (JM) in the same way that pexidartinib does, resulting in suppression of CSF1R and its downstream molecules on breast cancer cells." (PMID 35807438, 2022). "Our results demonstrate that CSF1-R expression on carcinoma cells detected by immunohistochemistry provides prognostic information in breast cancers, particularly in a subset of ER-positive cases, and may represent an actionable target for patient selection in trials evaluating CSF-1R blockade." (PMID 34830923, 2021). "Furthermore, we also determined the prognostic significance of CSF-1R+ tumor-associated macrophages and their association with lymphocytic infiltrates expressing immune checkpoint and CD163+ M2 macrophage biomarkers in the context of ER+ breast cancers." (PMID 34830923, 2021). "Non-invasive imaging of CSF1R mAb biodistribution could provide information regarding physiological distribution and tumor targeting and thereby support the rational design of combination strategies that include macrophage targeting for breast cancer." (PMID 34976826, 2021). "Given that CSF-1R inhibitors are under active study in clinical trials, including in breast cancer, positive CSF-1R staining in clinical breast cancer specimens and its association with immune cells could help identify which patients might best benefit from combination with immunotherapies." (PMID 34830923, 2021). "Indeed, depleting macrophages using CSF1-R-signaling antagonists improved outcomes in human breast cancer xenografts following combination chemotherapy (cyclophosphamide, methotrexate, and 5-fluorouracil) and in murine PyMT models following paclitaxel treatment." (PMID 33276524, 2020). "Interestingly, this pathway may be an adaptive response to anti-CSF1R therapy, as it was induced in CAFs following treatment with CSF1R inhibitor in models of colon, lung, breast carcinomas and melanoma." (PMID 31428105, 2019). "However, in humans CSF-1R is expressed in only about 50% of breast cancers." (PMID 23561040, 2013).
breast cancer (continued). "Preclinical models suggest that CSF-1R blockade enhances response to immune checkpoint inhibitors, and early-phase trials, such as NCT02880371, are evaluating this strategy in breast cancer." (PMID 40566067, 2025). "Treatment of mammary tumor-bearing mice with PLX3397 (Pexidartinib), a CSF-1R tyrosine kinase inhibitor, significantly reduced the number of TAMs and resulted in delayed tumor growth stimulated by an increase in CD8 + T cells and a decrease in CD4 + T cells." (PMID 39003350, 2024). "The preclinical result of emactuzumab, a CSF1R antibody, established its efficacy in targeting the CD163+ TAM population in breast cancer." (PMID 38715072, 2024). "Only CSF1R and EPHB2 (BL2 subtype-specific TK genes) were reported as having similar expression in different types of breast cancer, including TNBC." (PMID 36672350, 2023). "To address this need, here we developed an in vitro heterotypic human macrophage-ER+ PR+ HER2+ breast cancer cell 3D model, referred to as macrophage-tumor spheroid (MTS), and used it to investigate the effect of dual CSF1/CSF1R inhibition and CD40 activation." (PMID 37346794, 2023). "To our knowledge, we are the first who compared CD68, CD163, CSF-1R and CD206 for TAM detection and assessed their relation with clinicopathological characteristics in a large well-characterized series of intrinsic breast cancer subtypes." (PMID 36622544, 2023). "Currently, in the phase III trial for renal cell carcinoma and phase II trial for breast cancer, dovitinib has shown promising potential for solid tumours with an IC50 of 36 nmol/L against CSF1R." (PMID 37711590, 2023). "CSF1 activates its receptor (CSF1R) and subsequently activates PI3K and ERK signaling in HER2+ breast cancer cells." (PMID 38028209, 2023). "CSF1R and EGFR were tyrosine kinase receptors that regulated breast cancer cell growth and proliferation." (PMID 35807438, 2022). "To extend these results to two other cell lineages, we tested the C3-223 mammary cancer cell line and the NIH 3T3 fibroblast cell line where CSF-1R was overexpressed similarly to prostate C2H subclones." (PMID 36555673, 2022). "TAM subsets with high NRP1 co-expressed increased levels of CSF1R and decreased Ly-6C, indicating that NRP1 and NRP2 likely demark unique TAM subsets within murine mammary tumors." (PMID 35651620, 2022). "Here, we performed an exploratory analysis to examine the prognostic impact of CSF-1R+ carcinoma cells in the context of iTIL subsets expressing CD8 or FOXP3 in ER-positive breast cancers in the combined cohort of the BC Cancer series with complete 20-year follow-up information (n = 1666)." (PMID 34830923, 2021). "Clinically, M-CSF and its receptor, Colony Stimulating Factor-1 Receptor (CSF1R), were elevated in breast cancer patients with local invasion or metastasis compared to those without tumor spread, and their expression predicted poor survival." (PMID 34832904, 2021). "IL-34 increased the phosphorylation of MEK1/2, ERK1/2, JNK1/2, and c-Jun through CSF1R in mouse skin epidermal JB6 C141 cells and human breast cancer MCF7 cells." (PMID 33800170, 2021). "Another study also shows that simultaneous inhibition of CSF1R and SHP2 via dual-inhibitor-loaded nanoparticles (DNTs) is effective in mitigating tumors in breast cancer and melanoma mouse models." (PMID 32801364, 2020). "The inhibition of CSF-1R using the small drug PLX3397 was effective to deplete TAMs and to restore T cell migration into the TME of mouse mammary tumor models." (PMID 31878087, 2019). "Remarkably, in mouse mammary tumor models we found that the depletion of TAM with pexidartinib, an inhibitor of the colony stimulating factor 1 receptor (CSF1R), increased the motility of TIL and their ability to reach tumor cells." (PMID 31354719, 2019). "We used the ESTIMATE algorithm to correlate the extent of stromal cells with expression of IL-34, CSF-1, CSF-1R, PTPRZ1, and syndecan-1 in breast cancer tissue from the TCGA breast cancer dataset." (PMID 29796177, 2018).
breast cancer (continued). "In vitro experiments showed that tyrosine phosphorylation of CSF-1R, ERK, and FAK and cell migration are differentially regulated by IL-34 and CSF-1 in breast cancer cell lines." (PMID 29796177, 2018). "For example, using a CSF1R inhibitor (PLX3397 or BLZ945) to repolarize TAMs to the M1 type reduced tumour volume and prolonged survival time in both glioblastoma and breast cancer mouse models." (PMID 30373678, 2018). "Next, we examined the prognostic effect of CSF-1, CSF-1R, PTPRZ1, and syndecan-1 expression in the breast cancer TCGA dataset by generating Kaplan–Meier survival curves split in high (top 50%) and low (bottom 50%) gene expression." (PMID 29796177, 2018). "In breast cancer and renal cell carcinoma (RCC) autocrine signaling by CSF-1R was demonstrated in vivo and was modulated by TGFb1 and EGF, respectively." (PMID 27486763, 2016). "Because we profiled CSF-1R-induced and SRC-dependent changes in tyrosine phosphorylation in a mammary epithelial cell line, we first analyzed a small breast cancer dataset, derived from only eight tumors, available publicly from CST's PhosphoSitePlus®." (PMID 21049007, 2010). "Notably, another study conducted in metastatic breast cancer cells showed that in vivo CSF-1R up-regulation was mediated by TGF-β levels in the microenvironment, as in fact, the CSF-1R levels decreased upon TGF-β inhibition." (PMID 38254773, 2024). "The CSF-1 receptor (CSF-1R) is expressed on the surfaces of monocytes and TAMs; it has been reported that treatment with the CSF-1R inhibitor PLX3397 (Pexidartinib) depletes TAMs in tumors, including in mouse models of breast cancer and malignant peripheral nerve sheath tumors." (PMID 39000110, 2024). "Moreover, and importantly for our model choice, some HER2+ breast cancers have been shown to express both M-CSF1 and CSF1R fostering the crosstalk between this cancer subtype and TAMs." (PMID 37346794, 2023). "Together, these results showed that spp1/osteopontin is a target gene of the CSF-1/CSF-1R axis in both prostate and breast cancer cells but not in the NIH3T3 fibroblast cell line." (PMID 36555673, 2022). "Further, pharmacological inhibition of the anti-inflammatory BDM and/or microglial phenotypes, via either Colony Stimulating Factor 1 Receptor (CSF-1R) or STAT6 pathways, significantly decreased tumour burden in two different syngeneic mouse models of breast cancer brain metastasis." (PMID 35359423, 2022). "Furthermore, we found that, in breast cancer, the expression of three typical markers of TAMs (CD86, CSF1R, and CCR2) were positively correlated with SIPA1 and MYH9, respectively." (PMID 35453742, 2022). "For example, LY3022855, a CSF1R blocker used as a single agent or in combination with Durvalumab (anti-PDL1 mAb) or Tremelimumab (anti-CTLA4 mAb) for patients with a solid tumors, including breast cancers." (PMID 33747948, 2021). "This is interesting as in other tumor models, such as breast cancer, the sole inhibition of CSF-1R does not translate into antitumor activity but cooperates with cytotoxic agents." (PMID 33731849, 2021). "Interestingly, CSF1R inhibition depletes TAMs, enriches tumor-infiltrating CD8+ T cells, and attenuates the growth of cervical cancer and mammary tumors." (PMID 33800170, 2021). "IL-34 promoted cancer cell migration in basal MDA-MB-231 breast cancer cells independent of the CSF-1R, while it reduced cancer cell migration in HER2-positive SK-BR-3 cells." (PMID 29796177, 2018). "Thus, we analyzed potential mRNA expression differences of CSF-1, CSF-1R, PTPRZ1, and syndecan-1 between breast cancer samples and normal breast tissue samples from the TCGA breast cancer dataset." (PMID 29796177, 2018). "HCC1500 is, therefore, the only breast cancer cell line of the panel analyzed that we consider CSF-1R negative." (PMID 22096574, 2011).
breast cancer (continued). "This analysis indicated that the mean expression of CSF1 and CSF1R genes did not vary significantly (assessed by One-way ANOVA analysis) among breast cancer subtypes in either cell lines or in tumors samples." (PMID 22096574, 2011). "In both B16/F10 melanoma and 4T1 breast cancer models, the supramolecule demonstrated robust anti-tumor and anti-metastatic efficacy, suggesting that the simultaneous blockade of the CD47/SIRPα and CSF-1/CSF-1R signaling axes can be further explored as a potent immunotherapeutic strategy." (PMID 39457693, 2024). "Moreover, anti-CSF1R therapy combined with the adeno-TWIST1 vaccine resulted in tumor control, decreased metastasis, and a synergistic increase in CD8 T cell infiltration in 4T1 mammary tumors." (PMID 37505292, 2023). "Moreover, blocking the CSF1/CSF1R axis reduces mesothelioma growth and improves anti-PDL1 immunotherapy efficacy, and CSF1R inhibition minimizes the development of cervical and mammary tumors in mice by lowering TAMs turnover and increasing the CD8+ T-cell infiltration." (PMID 36303138, 2022). "Similarly, the supramolecule blocking the CD47-SIRPα signaling axis while sustainably inhibiting CSF-1R enhanced M2 to M1 repolarization within the TME and significantly improved antitumor and antimetastatic efficacies in animal models of melanoma and breast cancer." (PMID 31779710, 2019). "However, therapeutic targeting of CSF-1R restricts the recruitment of TAMs to primary sites in the MMTV-PyMT breast cancer model and reduces osteolytic bone lesions in nude mice injected intracardially with MDA-MB-231 breast cancer cells." (PMID 30823602, 2019). "In this article, correlative analysis of IL-34 expression and breast cancer prognosis stratified by PAM50 tumor subtype showed an unexpected prognostic relationship between intrinsic subtype and overall survival that demonstrated patterns contrasting previous studies analyzing CSF-1 and CSF-1R." (PMID 29796177, 2018). "Moreover, in silico analysis of comparative genomic hybridization datasets relative to 49 breast cancer cell lines and 67 primary tumors indicated the absence of CSF-1R or CSF-1 gene amplifications." (PMID 22096574, 2011). "When analyzed by Western blotting, we found no obvious difference in the strength of CSF-1R, ERK, and FAK activation between IL-34- and CSF-1-stimulated MCF-7 breast cancer cells." (PMID 29796177, 2018). "By contrast, in breast cancer and glioblastoma mouse models, PLX3397, another C-FMS/CSF-1R kinase inhibitor, did not affect primary tumor phenotype, but did improve the efficacy of cytotoxic chemotherapies and decreased tumor invasion, respectively." (PMID 23372702, 2013). "MYC and MAX RNA were detected in circulating breast cancer monocytes (KRT7+, CD11b+, CSF1R+), whole breast cancer tissue (KRT7+, CD11b+, CSF1R+), and isolated breast cancer tumor infiltrating macrophages (KRT7 negative or low, CD11b+, CSF1R+), supporting a potential role for MYC in human TAMs." (PMID 32685002, 2020).